RNU6-973P (RNA, U6 small nuclear 973, pseudogene)
Gene: Small nuclear RNA gene on chromosome 7 (65,859,660 to 65,859,766, reverse strand). Ensembl gene ENSG00000201560.
Homologues: Orthologues: chimpanzee U6 (99% identical), macaque U6 (93% identical). Paralogues in human: RNU6-1229P (97% identical), RNU6-1126P (90% identical), RNU6-26P (86% identical), RNU6-1024P (85% identical), RNU6-1060P (85% identical), RNU6-15P (85% identical), RNU6-166P (85% identical), RNU6-19P (85% identical), RNU6-266P (85% identical), RNU6-41P (85% identical), RNU6-949P (85% identical), RNU6-12P (84% identical), and 1287 more.